SRPK1 (SRSF protein kinase 1)
Diseases named in the same sentence as SRPK1 in open-access papers (continued):
Sharing a sentence is not in itself a finding about the gene and the disease.
cancer (continued). "In particular, upregulated expression of SRPK1 is frequently considered to be an oncogenic factor in a wide range of cancer types." (PMID 29283381, 2017). "It is possible that SRPK1 activates different downstream signalling pathways in different cancers, thereby resulting in various cellular processes being affected." (PMID 27859253, 2017). "Not only does this article implicate SRPK1 in yet another cancer type, but the findings are of particular interest because they demonstrate an alternative mechanism by which SRPK1 exerts its tumourigenic effects." (PMID 27859253, 2017). "SRPK1, a highly conserved protein in precursor mRNA translation and splicing, chromatin reconstruction, is dysregulated in different cancers." (PMID 28606154, 2017). "SRPK1 has been recently reported to be overexpressed in multiple cancers and exhibit pleiotropic effects that have been attributed to disturbed alternative splicing, which is a common feature of human tumors." (PMID 28858257, 2017). "Preferential splicing of proangiogenic VEGF is determined by serine-arginine protein kinase 1 (SRPK1), which is upregulated in a number of cancers." (PMID 26500332, 2016). "This has been widely reported for SRPK1, which is overexpressed in several cancer types, such as pancreatic carcinomas, breast and colon carcinomas, and lung cancer." (PMID 24069033, 2013). "Other reports using immunohistochemistry have found that the level of SRPK1 protein correlates with the grade of breast (n = 12) and colon (n = 15) cancer." (PMID 23236423, 2012). "Together, these studies suggest that SRPK1 is likely to play an important role in cancer development." (PMID 23236423, 2012). "Although SRPK1 is ubiquitously expressed in many tissue types, it is highly expressed only in testicular germ cells and is thought to be a cancer/testis-like antigen which usually has restricted tissue distribution." (PMID 23236423, 2012). "SRPK1 contributes to oncogenic pathways across cancers and is a promising therapeutic target." (PMID 41551143, 2025). "As such, under- or over-expression of SRPK1, can lead to constitutive Akt activation, offering a potential explanation for observations that SRPK1 levels can be downregulated or upregulated in different cancers." (PMID 36895328, 2023). "SRPK1’s role in cancer is not limited to the regulation of apoptosis." (PMID 36895328, 2023). "These analyses showed that SRPK1 was overexpressed in cancer tissue." (PMID 37091170, 2023). "The results shown here therefore suggest that SRPK1 could be a target in T cells in which PD-1 expression contributes to immune suppression in cancers." (PMID 37973660, 2023). "We therefore investigated whether inhibition of SRPK1 could prevent splicing to flPD1 and result in a reversal of cancer cell-mediated T cell exhaustion." (PMID 37973660, 2023). "Therefore, SRPK1 and 2 act as oncogenes, are expressed in the vast majority of cancers, and possess great potential as prognostic markers and possible therapeutic targets." (PMID 35463320, 2022). "Targeting SRPK1 as a cancer treatment has been tested on cell lines and animal models." (PMID 36038837, 2022). "In conclusion, SRPK1 activity is prognostic in many epithelial derived cancers." (PMID 35583632, 2022). "Focusing on SRPK1 specific inhibitors deserve further investigation on cancer treatment." (PMID 35192432, 2022). "The functions of SRPK1-2 in cancer are understood to a much greater extent than SPRK3." (PMID 35463320, 2022). "Aberrant SRPK1 expression is implicated in various signalling pathways associated with oncogenesis, a number of which, such as the PI3K/AKT, NF-КB and TGF-Beta pathway, are implicated in multiple different cancers." (PMID 35583632, 2022). "Of note, two of these articles investigated the role of SRPK1 in more than one cancer type." (PMID 35583632, 2022).
cancer (continued). "SRPK1 expression is also elevated in the precursor lesions of some epithelial malignancies, highlighting the enzymes likely role in the early stages of oncogenesis in such cancers." (PMID 35583632, 2022). "The levels of SRPK1 in cancer cells could be controlled at the transcriptional level by the Wilms' tumour suppressor (WT1), a zinc‐finger transcription factor shown to either repress or activate SRPK1 expression in different cellular contexts." (PMID 34092037, 2021). "However, the predicted inhibition of SRPK1 and of splicing regulation is also thought to contribute to the anti‐cancer efficacy of these treatments." (PMID 34092037, 2021). "Thus, it is possible that post‐translational modifications occur differently in cancers showing opposite prognostic potential of SRPK1, and contribute to its functional impact." (PMID 34092037, 2021). "Changes in expression of these microRNAs might contribute to modulate the cellular levels of SRPK1 in different cancer types." (PMID 34092037, 2021). "Similarly, a recent study revealed that either overexpression or knockdown of SRPK1 decrease the association between Akt and PHLPP1 and then interfere with PHLPP-mediated dephosphorylation of Akt, resulting in the promotion of cancer." (PMID 32989053, 2020). "SRPK1 promotes metastatic attributes in several cancer types, including breast cancer." (PMID 32859889, 2020). "This study provided novel specific inhibitors of SRPK1 from library of natural compounds database, which may be useful in the development of safe and effective anti-cancer agents." (PMID 33291073, 2020). "Additionally, SRPK1 exerts metastasis-promoting activities in a wide variety of cancers, including breast cancer." (PMID 32859889, 2020). "However, several preclinical studies on cell lines and animal models have tested the effect of aberrant SRPK1 expression on distinct oncogenic processes highlighting the potential role of SRPK1 as a therapeutic target in various cancers." (PMID 31861708, 2019). "In addition, targeting SRPK1 has enhanced sensitivity to platinum-based chemotherapy in some cancers." (PMID 31861708, 2019). "Of interest, existing evidence supports that SRPK1 acts heterogeneously among various cancer types." (PMID 31861708, 2019). "But, SRPK1 displays pleiotropic effects in various cancers and regulates different cellular properties which might be related to preferential activation of different downstream signaling pathways." (PMID 29100313, 2017). "This pleiotropy might be related to preferential activation of different downstream signalling pathways by SRPK1 in various cancers." (PMID 27859253, 2017). "As well as its potential use as a biomarker, the emerging evidence supporting the role of SRPK1 in the pathogenesis of several cancers, irrespective of its underlying mechanism, makes it a possible and indeed attractive therapeutic target." (PMID 27859253, 2017). "With this relationship in mind, it would be interesting to investigate whether CLK1 levels and/or activity vary across different cancer types and consequently modulate SRPK1 function." (PMID 27859253, 2017). "Taken together, these findings could mechanistically explain previous observations that SRPK1 could be found downregulated in some cancer contexts." (PMID 26273588, 2015). "Additionally, recent studies have shown that SRPK1 targeting is a reasonable strategy for cancer treatment due to the inhibition of angiogenesis." (PMID 26244849, 2015). "In further in vitro and in vivo studies, SRPK1 appeared to influence hepatocellular cell growth and malignancy suggesting that SRPK1 plays an oncogenic role and might be a potential therapeutic target in these cancer cells." (PMID 26273588, 2015). "SRPK1 overexpression has also been observed in several cancers, and so it is conceivable that its activation could also synergistically potentiate the oncogenic properties of SRSF1." (PMID 24101931, 2013).
cancer (continued). "Through modulation of selective splicing events, SRPK1 may allow cancer cells to enhance their proliferative, invasive, and angiogenetic potential." (PMID 24069033, 2013). "Thus, unlike the simpler yeast models, the relationship of SRPK1 function and cDDP resistance in human cancer cells requires further clarification." (PMID 23236423, 2012). "Notably, inhibiting SRPK1 altered the splicing program to produce the antagonistic isoform of PD-1, boosting T-cell destruction of cancer cells, and implying the potential application of small molecules targeting SRPK1 as innovative pharmacological immunotherapies." (PMID 39055714, 2024). "In addition, avβ3 integrin and SRPK1 signaling may defer considerably in different cancer cell lines." (PMID 36839704, 2023). "Hence, transcriptional regulation of specific microRNAs by HIF1α might induce the upregulation of SRPK1 under hypoxia that has been documented in multiple cancer cells." (PMID 34092037, 2021). "More research implied that SRPK1 may be a novel target for cancer diagnosis and therapy." (PMID 29100313, 2017). "Regarding the exact mechanism by which METTL3 and its target SRPK1 promote LUAD progression, we considered aerobic glycolysis because cancer cells prefer glycolysis over OXPHOS to provide sufficient biomass and energy for rapid proliferation." (PMID 39095708, 2024). "Despite this observation, SRPK1 and SRPK2 seem to act in different ways in cancer, depending on the cell type in which they are expressed." (PMID 36212152, 2022). "SRPK1 silencing was found to promote cleaved poly (ADP-ribose) polymerase (PARP) and b-cell lymphoma extra S (BCL-xS) expression in cancer cells." (PMID 35583632, 2022). "In our study, we also demonstrated that SRPK1 and SRSF1 were involved in the production of alternative splicing of VEGF-A165b in RCC cells and promoted cancer progression, which is consistent with the anti-angiogenic effect of VEGF-A165b in previous studies." (PMID 34544400, 2021). "It was demonstrated that SRPK1 functions as an oncogene by promoting the activation of PI3K/AKT signaling, a pathway involved in the development and progression of human cancer, very well described in lung cancer." (PMID 31934531, 2019). "Increases in SRPK1 and SRPK2 were observed in a wide range of distinct cancers, including breast cancer, colorectal cancer, lung cancer, ovarian cancer, hepatocellular carcinoma, pancreatic cancer, leukemia, and gliomas." (PMID 29283381, 2017). "SRPK1 and SRPK2 have also been observed to be overexpressed in various other human cancers, including pancreatic, breast, colon, lung and ovarian." (PMID 26244849, 2015). "Splicing factors, such as SR protein kinase 1 (SRPK1) or SRp55, were also shown to modulate alternative VEGF splicing under pathophysiologic conditions such as in experimental cancer settings." (PMID 24288605, 2013). "Other SRPK1 substrates such as, SF2/ASF and SC35 (SRp30b) splicing factors have also been shown to be overexpressed in several cancer types." (PMID 23236423, 2012). "And skipping exon 3 could generate the soluble PD-1, which was naturally produced in peripheral blood mononuclear cells and T cells, preventing cancer cells from suppressing T cell activity, which was regulated by SRSF1 and SR protein kinase 1 (SRPK1)." (PMID 39055714, 2024). "All conjugates retained mid nanomolar-level inhibitory activity against SRPK1 kinase and two out of four conjugates, geo75 and geo77 exhibited antiproliferative effects with low micromolar IC50 values against HeLa, K562, MDA-MB231 and MCF7 cancer cells." (PMID 36839704, 2023). "We found that SRPK1 expression was the second highest in TCGA and the CPTAC pan-cancer samples." (PMID 34193174, 2021).
cancer (continued). "Specific inhibition of SRPK1 decreases expression of VEGFxxx isoforms and has shown therapeutic effects in experimental cancers and eye pathologies without apparent side effects." (PMID 27999187, 2017). "Moreover, a detailed survey of immunohistochemical staining of human cancers indicated that SRPK1, KIF3B, C14orf142, NR2F1, and TMEM229B have significantly increased expression in the invasive zone of the primary tumors of these cancers as delineated by a pathologist." (PMID 29904055, 2018). "But the detailed roles and mechanisms of SRPK1 in cancer especially in HCC are not clear." (PMID 29100313, 2017). "Interestingly, SRPK1 is expressed in adult male germ cells, but generally not in most other normal adult tissues, suggesting a cancer/testis-like distribution." (PMID 23236423, 2012). "In addition, SRPK1 promotes cancer by regulating AKT phosphatase to induce AKT dephosphorylation by interacting with PHLPP1, which could dephosphorylate p-AKT, lead to AKT constitutive activation suggesting that SRPK1 plays a key role in signaling transduction." (PMID 34193174, 2021).
infection (9 papers, 2018 to 2025). The state of being infected such as from the introduction of a foreign agent such as serum, vaccine, antigenic substance or organism. "Inhibition of SRPK1 was shown to reduce replication, while blocking the activity of GSK-3 reduced viral replication in cells and lowered infection in patients." (PMID 39093972, 2024). "In the context of infection, ICP27 appears to play a dual role in inhibiting SRPK1 action on SR protein substrates." (PMID 31641093, 2019). "The ICP27 mutant plasmids were cotransfected with a plasmid expressing green fluorescent protein (GFP)-SRPK1 and subsequently infected with ICP27 null mutant virus 27-LacZ to recapitulate the conditions of infection." (PMID 31641093, 2019). "Indeed, inhibiting SRPK1 was found to reduce viral replication, while blocking GSK-3 activity decreased replication in cells and reduced infection in patients." (PMID 40858555, 2025). "Serine/arginine-rich splicing factor protein kinase-1 (SRPK1), syntaxin 12 (STX12) and ubiquinol-cytochrome c reductase hinge protein (UQCRH) from the upregulated group have been reported to be related to the infection and replication of certain kinds of viruses." (PMID 40920846, 2025). "However, further studies using infectious models are needed to validate the roles of SRPK1 and 2 in HBV replication and the pharmaceutical value of the docking groove of SRPK as a target in combating HBV replication and infection." (PMID 38324561, 2024). "While not proving SRPK1 as the infection-relevant HBc kinase the data suggest a mechanism whereby high-level HBc phosphorylation principally suppresses RNA binding whereas one or few strategic dephosphorylation events enable selective packaging of the pgRNA/polymerase complex." (PMID 30566530, 2018). "However, SRPK1 expression might be increased after 10 d of symptom onset, and the expression of KLF5 significantly differed between severe patients in the early and late stages of infection." (PMID 38262689, 2024).
adenocarcinoma (1 paper, 2012). A common cancer characterized by the presence of malignant glandular cells. "In this study, we investigated the status of SRSF1, SRSF2 and its phosphorylated form P-SRSF2, as well as of SRPK1 and SRPK2 in a series of 107 NSCLC, including 54 adenocarcinoma (ADC) and 53 squamous cell carcinoma (SCC)." (PMID 23071587, 2012).
neurodevelopmental disorder (1 paper, 2024). A behavioral and cognitive disorder with onset during the developmental period that involves impaired or aberrant development of intellectual, motor, or social functions. "This article presents evidence that SRPK1 has distinct spatiotemporal expression patterns enriched in processes related to neurodevelopmental disorders across development." (PMID 38376036, 2024). "This article presents evidence for distinctive SRPK1 expression patterns enriched in processes related to neurodevelopmental disorders across development." (PMID 38376036, 2024). "Additionally, using the GTEx version 8 dataset for analysis, the present study revealed that genes significantly coexpressed with SRPK1 were also significantly coexpressed in neurodevelopmental disorders in adult humans." (PMID 38376036, 2024).
SRPK1 also shares sentences with these, for which no sentence is quoted: acute lymphoblastic leukemia (2 papers); cutaneous melanoma (2); diabetes (2); Autoimmunity (1); basal cell carcinoma (1); bladder cancer (1); blue nevus (1); cervical squamous cell carcinoma (1); childhood asthma (1); epidermoid-carcinoma (1); erectile dysfunction (1); esophageal cancer (1); germ cell tumor (1); head and neck cancer (1); infectious disease (1); Intellectual disability (1); lung disease (1); lymphoid leukaemia (1); myeloma (1); neuroblastoma (1); neurodegenerative disease (1); NK/T-cell lymphoma (1); osteoarthritis (1); ovarian serous cystadenocarcinoma (1); Parkinson disease (1); pregnancy hypertension (1); rectum adenocarcinoma (1); renal carcinoma (1); sarcoma (1); soft tissue sarcoma (1).
A further 2 diseases each share a sentence with SRPK1 in 1 paper.